IL7 (interleukin 7)
Diseases named in the same sentence as IL7 in open-access papers (continued):
Sharing a sentence is not in itself a finding about the gene and the disease.
hematological malignancies (9 papers, 2019 to 2026). "In addition to hematologic malignancies, IL-7/IL-7R signaling is implicated in the progression of various solid tumors." (PMID 41596598, 2026). "IL-7 serves as a growth factor in the process of hematopoiesis, promoting the proliferation and differentiation of hematological malignancies and stimulating immunological responses in fully developed T-cells." (PMID 38464517, 2024). "The role of IL-7 and IL-15 in contributing to CAR-T proliferation and/or engraftment has been described extensively in hematological malignancies." (PMID 31651363, 2019). "In conclusion, in patients with hematological malignancies who underwent cell therapies, the ability to acutely upregulate IFN-γ and IP-10/CXCL10 at the priming vaccination and IFN-γ, IL-15, IL-7 and IL-10 upon booster vaccination were predictive of successful Ab development." (PMID 35693807, 2022). "Studies of IL-7, which promotes T cell function, found that IL-7 may confer a survival benefit but in PML secondary to hematologic malignancies and post-transplant immunosuppression patients but not underlying HIV." (PMID 40621097, 2025).
bacterial infection (8 papers, 2011 to 2025). "Recently others and we have evidenced an overexpression of interleukin-7 (IL-7), a cytokine constitutively expressed by mucosal epithelial cells, in tissues following viral and bacterial infections." (PMID 33717097, 2021). "IL7 is a crucial cytokine, usually secreted by intestinal epithelial cells in response to bacterial infections, which contributes to the organization of secondary lymphoid structures." (PMID 28587282, 2017). "More interestingly, IL7 secretion is promoted by glucocorticoids in an α diurnal base, supporting T cell distribution and, thus, immune response to various soluble antigens or bacterial infections at night." (PMID 39062927, 2024). "Furthermore, 28 pregnancy regulated genes were found only in the endometrium of cows following bacterial infection and these were associated with altered iNOS, TLR, and IL-7 signaling pathways." (PMID 35358206, 2022). "In this context, we suggest a potential role for GM-CSF and IL-7 in modulating B and neutrophil dynamics during severe systemic infection (e.g., SARS-CoV-2) and bacterial infections." (PMID 39012145, 2024).
inflammation (6 papers, 2012 to 2025). Aberrant reaction of the microcirculation characterized by movement of fluid and leukocytes from the blood into extravascular tissues. "The other group of cytokines associated with acute eosinophilic inflammation was IL-4 and IL-7." (PMID 35387066, 2021). "Studies have shown that certain drugs can successfully treat lung inflammation by blocking the IL-7/IL-7R pathways between macrophages and epithelial cells." (PMID 40333951, 2025). "IL-7 is a crucial mediator of T cell development and is contributing to endothelial inflammation via inducing monocyte recruitment." (PMID 33319833, 2020).
cardiovascular disease (5 papers, 2016 to 2024). "In relation to cardiovascular diseases, IL-7 acts as a regulator of T cell homeostasis with involvement in inflammatory processes and has been demonstrated to drive atherogenesis and promote plaque instability." (PMID 38930112, 2024). "Myokines, including fibroblast growth factor-23 (FGF-23), tumour necrosis factor-related apoptosis-inducing ligand receptor 2 (TRAIL-R2), interleukin-7 (IL-7), and monocyte chemoattractant protein-1 (MCP-1), among others, have been implicated in cardiovascular diseases." (PMID 38930112, 2024). "The associations were attenuated but many remained statistically significant in the full sample (IL‐6, IL‐7, IL‐8, LIF‐R, and LAP TGF‐beta‐1) after adjustment for cardiovascular disease and risk factors, suggesting additional biologic pathways play a role in these associations." (PMID 37584418, 2023). "IL-7 was found to be an important predictor of PAD prognosis, as it may be involved in various mechanistic pathways important for cardiovascular disease development and progression." (PMID 38930112, 2024). "In our study, by inputting hsa-miR-200c-3p, IL-7, VCAM-1 and VEGF-C into the IPA analysis together with glucose to simulate the diabetic state, we predicted that downregulated miR-200c may lead to cardiovascular disease through VEGF signaling and PI3K/Akt signaling pathways." (PMID 36555301, 2022).
hematological cancers (4 papers, 2021 to 2025). "The IL-7/IL-7R axis has been well characterized in the context of immune development and hematologic cancers." (PMID 41360767, 2025). "Indeed, IL-7/IL-7R-mediated signaling plays an oncogenic role in hematological tumors by may being resistant to conventional chemotherapy and targeted therapeutics." (PMID 34575268, 2021).
heart disease (3 papers, 2018 to 2025). "However, non-IFN-γ synthesizers had lower STAT-5 phosphorylation, less IL-7 receptor functionality, and reduced CD25 regulation (mainly in those with severe heart disease) in CD4+ T cells, accompanied by lower Bcl-2 expression in TCD4+ and TCD8+ cells after IL-7 stimulation." (PMID 39907396, 2025). "Addition of IL-7 or IL-27 in short-term cultures with T. cruzi antigens increased the number of IFN-γ-producing T cells in response to T. cruzi in IFN-γ producers but not IFN-γ nonproducers in patients with no signs of cardiac disease and patients with some degree of cardiac dysfunction." (PMID 30517089, 2018). "IFN-γ nonproducers with cardiac disease (i.e., subjects of the G1, G2 and G3 clinical groups) exhibited lower frequencies of phosphorylated STAT5+ (pSTAT5) in CD4+ T cells than IFN-γ producers and uninfected subjects, in response to IL-7." (PMID 30517089, 2018).
metabolic disease (3 papers, 2012 to 2024). A congenital disorder (due to inherited enzyme abnormality) or acquired (due to failure of a metabolically important organ) disorder resulting from an abnormal metabolic process. "Collectively, our findings indicate that the immune cytokine IL-7 could participate to the development of metabolic diseases through the modulation of the white adipose tissue." (PMID 22768283, 2012).
respiratory disease (3 papers, 2022 to 2023). "Five individual mediators were different among the cohorts (MCP‐1, IL‐7, IL‐10, IL‐13, and IL‐15) with lower concentrations in the groups with respiratory disease, particularly COPD and CRS." (PMID 36780897, 2023). "Our findings on IL-7 and its effects on lower respiratory diseases will be important for expanding the utility of therapeutics that are currently available." (PMID 34997007, 2022).
colonic polyps (2 papers, 2020 to 2024). "IL-7 signals are involved in the development of chronic intestinal inflammation and human intestinal diseases." (PMID 33585004, 2020).
degenerative diseases (2 papers, 2022 to 2025). "This dual and contradictory mechanism renders the role of IL‐7 in central neurodegenerative diseases uncertain." (PMID 40922636, 2025). "In cord blood cells, IL-7 increased telomere length and hTERT gene expressions, suggesting that it may also protect against cellular senescence in other degenerative diseases." (PMID 36186138, 2022).
inflammatory myopathy (1 paper, 2022). "To further explore the expression of the receptors for the 8 differentially expressed cytokines (Eotaxin, IL7, IL18, IP10, MCP1, MCSF, MIG and SCGFβ) in inflammatory myopathy, we used the ligand-receptor database (ramilowski_pairs) in the R package celltalker." (PMID 35517781, 2022).
renal disease (1 paper, 2015). ",A number of anti-fibrotic agents, including Norcantharidin, Cordyceps sinensis, IL-7, proteasome inhibitor(MG132 and lactacystin), mycophe and PXS25 have been shown to inhibit the TGFβ1-induced Smad2 pathway in both animal models of renal disease and in cultured tubular cells." (PMID 25658916, 2015).
vascular disorder (1 paper, 2025). A general term used to describe any disease affecting blood vessels]. "IL-7 has also been identified as a significant mediator in vascular inflammation, promoting the recruitment of monocytes and macrophages to the endothelium, a process implicated in various vascular disorders." (PMID 39857734, 2025).
IL7 also shares sentences with these, for which no sentence is quoted: Cognitive impairment (5 papers); Alzheimer disease (4); prostate tumor (4); ankylosing spondylitis (3); blood cancers (3); chronic myelogenous leukemia (3); dementia (3); hemophagocytic lymphohistiocytosis (3); nosocomial infection (3); Thrombocytopenia (3); adenocarcinoma (2); atopic asthma (2); benign ovarian tumors (2); chronic lymphocytic leukemia (2); combined immunodeficiency (2); demyelinating disease of the central nervous system (2); dermatitis (2); glaucoma (2); gout (2); juvenile idiopathic arthritis (2); leishmaniasis (2); lipodystrophy (2); malignant mesothelioma (2); metastasis (2); neurologic diseases (2); neuromyelitis optica (2); Primary Immunodeficiency (2); rheumatic diseases (2); Shock (2); systemic inflammatory response syndrome (2).
A further 130 diseases each share a sentence with IL7 in 1 paper.